RHOA (ras homolog family member A)
Diseases named in the same sentence as RHOA in open-access papers (continued):
Sharing a sentence is not in itself a finding about the gene and the disease.
gastric cancer (continued). "Due to a scarcity of RHOA reviews in the field of gastric cancer (GC), our focus herein is limited to RHOA, and its related GTPase family members in GC." (PMID 31156701, 2019). "A study shows that the RhoA guanine exchange factor NET1, which is a factor in the metastasis of gastric cancer, isoforming with short 3′ UTR, promotes cellular migration and invasion in vitro, but CFIm25 and metastases in HCC has not been studied." (PMID 29545935, 2018). "Fbxw7, an Ub E3 ligase containing F-box and WD repeat domain, suppresses gastric cancer cell motility and invasion by inducing the ubiquitination and degradation of both total RhoA and GTP-RhoA." (PMID 29080116, 2018). "Reduction of GBM43 migration following STAT3 inhibition validated previous studies where STAT3 silencing impaired the migration of gastric carcinoma and GBM cells, likely due to decreased activity of RhoA and matrix metalloproteinases (MMPs) expression." (PMID 29566069, 2018). "In gastric cancer cells, down-regulation of PI3K/Akt/GSK3β signaling in SGC-7901 cells suppressed Wnt5a-induced activation of RhoA." (PMID 28289332, 2017). "Recently, both CMKLR1 and GPR1 were found to signal through the RhoA/Rock pathway in HEK293A and gastric carcinoma cells." (PMID 29221117, 2017). "Transforming growth factor-β1 significantly upregulated the activity of RhoA and myosin phosphorylation, whereas TGF-β1 decreased ZO-2 and E-cadherin expression in scirrhous gastric cancer cells." (PMID 20145621, 2010). "As well as highlighting the importance of NET1 and RhoA in cell invasion, these data demonstrate that both NET1 and RhoA bioactivities are essential in LPA-induced gastric cancer cell migration and invasion." (PMID 18827818, 2008). "Lysophosphatidic acid-induced cell invasion and migration were significantly inhibited using either NET1 siRNA or a RhoA inhibitor (C3 exoenzyme), thus indicating the activity of both NET1 and RhoA in gastric cancer progression." (PMID 18827818, 2008). "An RNAi approach using an siRNA duplex specifically targeting NET1 mRNA was used to investigate the effect of NET1 knockdown on RhoA activation and AGS gastric cancer cell migration and invasion." (PMID 18827818, 2008). "Furthermore, the suppression of tumor growth using an inhibitor of the RHOA downstream effector, ROCK, suggests DLC1 as a druggable target for gastric cancer." (PMID 36984515, 2023). "Indeed, our works prove that RhoA activation and upregulation trigger LIMK/cofilin signaling, providing a reliable clue for gastric cancer cell metastasis." (PMID 33875796, 2021). "In liver cancer and gastric cancer, YAP has been shown to promote motility and metastasis, but there have been few studies to date exploring the mechanistic relationship between RhoA and YAP in the context of PDT-induced OS cell apoptosis." (PMID 34627383, 2021). "In recent study, RhoA and RhoC expression are elevated, while RhoB expression is downregulated or absent in gastric cancer tissues, compared to normal gastric tissues." (PMID 32392742, 2020). "Similar to others findings, here we found that hypoxia elevated both Rac1-GTP and Cdc42-GTP levels, but not RhoA-GTP in gastric cancer cells." (PMID 31019460, 2019). "The studies have shown that genetic alterations in the RhoA pathway, including recurrent RHOA mutations and RhoGAP fusion along with the CDH1 mutations, are quite common in DGC but not in other variants of gastric cancer." (PMID 30115886, 2018). "Similarly, WNT-5A induces migration in gastric cancer cells by activating PI3K/AKT pathway which phosphorylates and inactivates GSK-3β and activates RhoA leading to cytoskeleton remodeling." (PMID 26514730, 2016). "Interestingly, in SGC-7901 gastric cancer cells, CD24 was shown to maintain the expression of EGFR through a RhoA-dependent manner." (PMID 26830684, 2016).
gastric cancer (continued). "Taken together, these results suggest that NKX6.3 may suppress gastric cancer cell migration and invasion by inhibiting the Myc-p300/CBP-Skp2-Miz1 transcriptional complex formation required for RhoA expression." (PMID 27333045, 2016). "Alternatively, ongoing studies in our laboratory have revealed that Rac1, but not RhoA or Cdc42, is activated in RhoGDI2-overexpressing gastric cancer cells." (PMID 24185104, 2013). "Interestingly RhoA, which our group have previously shown to be regulated by NET1 in gastric cancer, has also been shown to activate TGFβ." (PMID 23945136, 2013). "Rho/Rho-associated protein kinase (ROCK) pathway also plays a key role in gastric cancer cell metastasis and invasion by recruiting IQ domain GTPase activating protein 1 (IQGAP1) 13-16, while IL-6 induces gastric cancer cell invasion by activating the c-Src/RhoA/ROCK signaling pathway." (PMID 40092690, 2025). "Several anoikis resistance related signal pathways have been reported in GC, including RhoA pathway, Wnt/β-catenin signaling pathway and EGFR signaling pathway, and these pathways promote angiogenesis, lymph node metastasis and peritoneal metastasis of gastric cancer cells." (PMID 36925640, 2023). "Results showed that expression levels of NKX6.3, CDH1, CDKN1A, and EP300 were decreased while expression levels of NFκB p65, AICDA, CBFβ, APOBEC3A, APOBEC3B, RhoA, ROCK1, ROCK2, PIK3CA, and CCND1 were increased in CagA positive gastric cancers compared to those in CagA negative cases." (PMID 30514953, 2018). "Furthermore, we found that NKX6.3 functions as a negative transcriptional regulator of RhoA, Cdc42, Rac1, Rac2, Skp2 and c-Myc genes and completely inhibits c-Myc-p300/CBP-Skp2-Miz1 and Max complex formation, thereby preventing gastric cancer cell migration and invasion." (PMID 27333045, 2016).
melanoma (119 papers, 2009 to 2026). A malignant, usually aggressive tumor composed of atypical, neoplastic melanocytes. "In melanoma, high level of actomyosin contractility due to RHOA/ROCK pathway has been associated with amoeboid migration of melanoma cell lines as well as resistance to shear forces during extravasation." (PMID 36059552, 2022). "RhoA has also been reported to be associated with the adhesion process of BC and melanoma cells, through the regulation of integrins and the capability of tumour cells to adhere to basal membrane components." (PMID 36009536, 2022). "Amoeboid transition has been previously linked to cancer stemness in melanoma cells, and RhoA has been directly associated with the expression of stem‐like features." (PMID 34532864, 2021). "This is applicable to the present study, in which we found that inhibition of RhoA signaling by the RhoA‐GEF inhibitor Rhosin in WNT5A‐deficient melanoma cells resulted in an even more significant reduction in melanoma cell invasion than WNT5A knockdown alone." (PMID 33969605, 2021). "Recently, the role of RHOA in the effects caused by UV radiation in metastatic melanoma cells was assessed." (PMID 33072757, 2020). "In fact, RhoA activation was previously linked to global microfilament reorganization and epithelial-to-mesenchymal transition of melanoma cells." (PMID 29435180, 2018). "RhoA and RhoC have been strongly implicated in the aggressiveness and metastasis of a number of cancer types, including breast, prostate, and melanoma, but the precise mechanisms underlying those effects are not clear." (PMID 27600078, 2016). "Further studies are required to understand the mechanism of RhoC increase, as this gene has been implicated as an independent mitogen from RhoA, and can induce metastasis in melanoma cells." (PMID 25188245, 2014). "In tumor cells such as melanoma cells, cytoplasmic protrusions are associated with amoeboid fast migration, and are initiated by actomyosin contractility following RhoA activation." (PMID 24498100, 2014). "EphA2 receptor activation by its cognate ligand ephrinA1 is a powerful signal to activate RhoA and its overexpression and activation causes achievement of amoeboid invasive styles from both prostate carcinoma and melanoma cells." (PMID 20822528, 2010). "Furthermore, the CD146 and ERM complex associates with RhoGDI1, spatially sequestering it from RhoA, and then enhancing melanoma cell migration by activated RhoA." (PMID 39768163, 2024). "This suggests that the mutational signature of melanoma cells determines whether RHOA acts as an oncogene or a tumor suppressor." (PMID 34503171, 2021). "We next explored the possible impact of the combined opposite targeting of p110δ PI3K and RhoA on SCC tumour progression which is a non-melanoma skin cancer." (PMID 38182748, 2024). "Atg5 not only mediates a positive feedback loop between the Wnt signaling pathway and autophagy in melanoma cells, but also regulates cell polarity and movement through the activation of the RhoA and Jun N‐terminal kinase (JNK) signaling cascades." (PMID 38826147, 2024). "RPM exposure of BL6-10 cells (highly lung-metastatic B16 melanoma cell line) inhibited cell proliferation/metastasis via the FAK/RhoA-regulated mTORC1 pathway." (PMID 37048115, 2023). "Our next step was to analyze the level of total RhoA in BRAFi-sensitive and BRAFi-R melanoma cells by Western blotting." (PMID 36551563, 2022). "In our search for an alternative explanation for the increased activity of MARCKS in BRAFi-R melanoma cells, we found elevated basal activities of PKCα, PKCε, PKCι, and RhoA." (PMID 36551563, 2022). "Our results revealed that BRAFi-sensitive A375, A375-R1 and A375-R2 melanoma cells exhibited similar expression levels of RhoA." (PMID 36551563, 2022).
melanoma (continued). "We then unravel the molecular mechanism by which SEMA6A regulates the remodeling of actin cytoskeleton thereby sustaining the aggressive behavior of BRAF-mut melanoma cells, and show the involvement of downstream RhoA-YAP cascade." (PMID 35440004, 2022). "This possibility is of particular interest for the present study since the WNT5A ligand has been demonstrated to activate both PKC and RhoA signaling in human melanoma cells." (PMID 36551563, 2022). "Together, these observations indicate that RhoA-myosin II pathway is critical for YAP enhanced soft side biased migration in melanoma cells." (PMID 36428972, 2022). "In search of explanation for enhanced MARKS activity in BRAFi-R melanoma cells, we found elevated basal activities of PKCα, PKCε, PKCι, and RhoA." (PMID 36551563, 2022). "Using this indirect approach to estimate RhoA activation, the authors found increased RhoA activity in only half of the developed BRAFi-R melanoma cell lines." (PMID 36551563, 2022). "Immunohistochemistry for our 3D melanoma model showed that Cdc42, Rac1, and RhoA were constitutively expressed in the nuclei of melanoma cells of the untreated group, and NX-5 treatment decreased their expression." (PMID 34201921, 2021). "In this study, we demonstrated that CH is efficient in blocking the amoeboid motility of metastatic melanoma cells by decreasing EphA2 expression and RhoA activation." (PMID 34298765, 2021). "To date, numerous in vitro studies have investigated the contribution of RHOA-mediated signaling in melanoma cells." (PMID 34503171, 2021). "Immunohistochemistry showed that Cdc42, Rac1, and RhoA were constitutively expressed in the nuclei of melanoma cells of the untreated group, and NX-5 treatment decreased their expression." (PMID 34201921, 2021). "Our previous study showed that overexpression of RhoA/C correlates with poor overall survival in melanoma patients." (PMID 33406809, 2021). "The results suggest that dual targeting of WNT5A and RhoA activity is a more efficient approach to impair melanoma cell invasion than inhibiting each target alone." (PMID 33969605, 2021). "The use of an inhibitor of Rho kinase (ROCK), which is modulated by RhoA, has been shown to resensitize melanoma cell lines to BRAF inhibitors." (PMID 33807778, 2021). "Using the 3D melanoma model prepared in this way, the reduction in the expression of Rho-family GTPase (Cdc42/Rac1/RhoA) protein by NX-5 treatment was confirmed by immunohistochemical staining." (PMID 34201921, 2021). "For instance, pro-invasive effects have been reported in melanoma cells in vitro, due to upregulation of N-cadherin expression and RhoA activity inhibition." (PMID 34358096, 2021). "EPHA2, which is highly expressed in dedifferentiated/invasive melanoma cells, stimulates RhoA activity and promotes amoeboid migration." (PMID 33802847, 2021). "RhoA activation occurs in 50–60% of melanoma cell lines resistant to vemurafenib, likely as a result of transforming growth factor beta (TGF-β)." (PMID 33807778, 2021). "We next found that dual targeting of WNT5A and RhoA more effectively reduced melanoma cell invasion than targeting either protein individually." (PMID 33969605, 2021). "Our previous study has shown that RhoA/C overexpression was involved with poor prognosis in patients with malignant melanoma." (PMID 33406809, 2021). "As we found several RhoGEFs and ROCK1/2 to be increased during melanoma progression, we first investigated which proteins were binding RhoA in melanoma cells." (PMID 34172930, 2021). "CD146 activated RhoA leads to increased RhoA activity and migration of the melanoma cells through the activation of the PIP5Ks/AKT pathway, a lipid kinase which plays a role in cancer cell evasion and cell survival through the PI3K/AKT pathway." (PMID 34439879, 2021). "Accordingly, Guo and co-authors demonstrated that in melanoma cells AMPK-mediated inhibition of RhoA decreases cell invasion and migration." (PMID 34298765, 2021).
melanoma (continued). "Our previous reports confirmed that Smad2/3 and Par6/aPKC/RhoA pathways upregulate the expression of Vimentin along with aPKCs in melanoma cells." (PMID 33525953, 2021). "Our results suggest that dual targeting of WNT5A and RhoA signaling is a more effective strategy for controlling the invasion of BRAF wild‐type and BRAFV600 mutated melanomas treated with a BRAF inhibitor than targeting either of the proteins individually." (PMID 33969605, 2021). "In the human melanoma cell line A375, silencing of Cullin3 results in elevation of RhoA protein levels, indicating that a Cullin3 E3 ligase complex regulates RhoA in this cell type as well." (PMID 34136490, 2021). "Further examination of the role mitochondrial fission and fusion plays, and the influence of RHOA signaling on this morphology shift, would contribute to the understanding of melanoma metabolism." (PMID 34831420, 2021). "For that purpose, RHOA was constitutively expressed or silenced in melanoma cells and subsequently the cells were exposed to UV." (PMID 33072757, 2020). "In melanoma cell lines, depletion of PAK4 was associated with an increase in RhoA activity and a decrease in the percentage of cells with mature degradative invadopodia." (PMID 32309283, 2020). "RHOA silencing was found to induce an increase in melanoma sensitivity to UV, increasing the number of DNA damages caused and dramatically reducing melanoma cell motility and invasion." (PMID 33072757, 2020). "Consistent with with the findings in melanoma cells, microgravity was found to regulate the focal adhesions and associated signaling molecules in glioma cells (U251 cells), such as FAK and RhoA/Rock." (PMID 32344794, 2020). "Rescue studies using constitutively active Ras and Rho activator calpeptin demonstrated that ropivacaine inhibited migration mainly through RhoA whereas growth and survival were mainly inhibited through Ras in melanoma cells." (PMID 32085741, 2020). "The first evidence of the role of ET-1 in invadopodia formation has been highlighted in human melanoma cells, where ET-1 through Gi activates Cdc42 GTPase while decreasing RhoA." (PMID 33178698, 2020). "We further detected a global reduction of downstream signaling of Ras and RhoA in ropivacaine-treated melanoma cells." (PMID 32085741, 2020). "Altogether, these data indicate that DLC1 is required to promote the invasiveness, tumorigenicity, and proliferation of melanoma cells in a RHOA-independent manner." (PMID 32214200, 2020). "Clinically, CDC42, RAC1, and RHOA expression in patient samples can provide relevant knowledge about melanoma thickness, ulceration, prognosis, and drug resistance." (PMID 33072757, 2020). "Despite the reduced number of samples (n = 134), this is the first published study to analyze RHOA expression in patient-derived melanoma samples." (PMID 33072757, 2020). "In the last decades, the role of Cdc42, Rac, and RhoA, the best-characterized members of this family, was extensively explored in relation to melanoma cell motility." (PMID 33072757, 2020). "Similar to ropivacaine, we found that lidocaine also significantly decreased the activities of RhoA, Rac1 and Ras in melanoma cells." (PMID 32085741, 2020). "As such, RHOA can regulate DNA repair mechanisms, playing a central role in protection against UV radiation, by mediating genomic stability of melanoma cells." (PMID 33072757, 2020). "We found that ropivacaine significantly decreased RhoA, Rac1 as well as Ras activities in melanoma cells." (PMID 32085741, 2020). "Inhibition of the RhoA transcriptional program through ROCK inhibitor treatment re-sensitizes dedifferentiated melanoma cells to BRAFi treatment in vitro." (PMID 32466585, 2020).